OGDHL (oxoglutarate dehydrogenase L)
Diseases named in the same sentence as OGDHL in open-access papers (continued):
Sharing a sentence is not in itself a finding about the gene and the disease.
childhood disintegrative disorder (1 paper, 2022). A rare pervasive developmental disorder with a disease onset before the age of three and characterized by a dramatic loss of behavioral and developmental functioning after atleast two years of normal development. "Furthermore, aberrant OGDHL copy number may be associated with childhood disintegrative disorder." (PMID 35370858, 2022).
chronic kidney disease (1 paper, 2025). Impairment of the renal function secondary to chronic kidney damage persisting for three or more months. "Studies indicate that the transcriptional repressor REST is upregulated in chronic kidney disease, where it directly binds to the OGDHL promoter and represses its transcription." (PMID 41463550, 2025).
clear cell renal cell carcinoma (1 paper, 2025). "In clear cell renal cell carcinoma (ccRCC), oxoglutarate dehydrogenase-like (OGDHL) is notably down-regulated, leading to the inhibition of lipid synthesis." (PMID 40483535, 2025).
depression (1 paper, 2022). "Only four SNV variants were considered to have high penetrance for depression: OGDHL rs2293239, TBX1 rs41298838, IL16 rs201457933, and FBXO15 rs79499419." (PMID 35370858, 2022). "First, a series of bioinformatic analyses indicated that the OGDHL rs2293239 variant had a strong association with depression onset in the present family." (PMID 35370858, 2022). "Compared with TBX1, IL-16, and FBXO15, we found that OGDHL was strongly associated with depressive disorders in a range of different aspects." (PMID 35370858, 2022). "We identified a novel rare variant of OGDHL, rs2293239, that may serve as the driving force for depression onset in a Chinese pedigree." (PMID 35370858, 2022). "This previous work strongly supports our speculation that the rs2293239 mutation likely impairs OGDHL catalytic activity, thus resulting in increased intracellular glutamate and eventually inducing depression." (PMID 35370858, 2022). "It is therefore reasonable to suspect that the changes in cerebral substructures caused by OGDHL rs2293239 may account for the depressive disorders of this family." (PMID 35370858, 2022). "Taking all of our results and the evidence from previous literature together, we propose that OGDHL rs2293239 is likely one of the major genetic driving forces of depression onset in the present family, via the following mechanism." (PMID 35370858, 2022). "Together, these findings suggest that OGDHL rs2293239 is connected with depression." (PMID 35370858, 2022). "Therefore, it was considered that the OGDHL rs2293239 variant was unlikely to induce depression by interfering with cerebral cortex activity in this family." (PMID 35370858, 2022). "In particular, a non-synonymous single nucleotide variation in the oxoglutarate dehydrogenase-like (OGDHL) gene, rs2293239 (p.Asn725Ser), was identified as one of the major driving genetic forces for depression onset in the family." (PMID 35370858, 2022).
diabetic nephropathy (1 paper, 2025). "Specifically, in a diabetic nephropathy model, glomerular podocyte injury involves mitochondrial dysfunction, including irregular dynamics, and it can be inferred that OGDHL plays a potential role in developing DKD." (PMID 40376698, 2025).
microcephaly (1 paper, 2023). A congenital or acquired developmental disorder in which the circumference of the head is smaller than normal for the person's age and sex. "Variants in OGDH, OGDHL, and DHTKD1 isoenzymes have been associated with various clinical phenotypes, including microcephaly." (PMID 38031187, 2023).
Myocardial fibrosis (1 paper, 2022). "The data then suggested that the metabolism-related gene OGDHL was associated with myocardial fibrosis of DCM and probably a biomarker for myocardial remodeling in patients with DCM." (PMID 35463769, 2022).
myocardial infarction (1 paper, 2023). Gross necrosis of the myocardium, as a result of interruption of the blood supply to the area, as in coronary thrombosis. "Evans Blue/TTC double staining revealed that OGDHL overexpression attenuated the effect of mVNS in reducing myocardial infarction size." (PMID 37957640, 2023).
neuroblastoma (1 paper, 2025). Neuroblastoma (NB) is the most common solid, extracranial childhood tumor. "In agreement with our findings for Ogdh1, also OGDHL-deficient human neuroblastoma cells were shown to reduce oxygen consumption." (PMID 40904733, 2025).
Parkinson disease (1 paper, 2025). A progressive degenerative disorder of the central nervous system characterized by loss of dopamine producing neurons in the substantia nigra and the presence of Lewy bodies in the substantia nigra and locus coeruleus. "Furthermore, recent research has shed light on the involvement of OGDHL in Parkinson’s disease (PD) pathogenesis." (PMID 41463550, 2025).
prostate carcinoma (1 paper, 2023). A carcinoma that arises from epithelial cells of the prostate gland. "OGDHL and ASNS alterations and their association with prostate cancer patient survival (a proxy of tumour aggression) were investigated in cBioPortal." (PMID 37196186, 2023).
rectal cancer (1 paper, 2020). A primary or metastatic malignant neoplasm that affects the rectum. "rs7511595 T > C in the OGDHL gene had a significant association with a decreased risk of rectal cancer (CC, 0.60 [0.40–0.92] compared to TT)." (PMID 33053772, 2020).
Stroke (1 paper, 2020). Sudden impairment of blood flow to a part of the brain due to occlusion or rupture of an artery to the brain. "Conversely, five genes (CLCN6, OGDHL, COL6A3 [MIM: 120250], INSR [MIM: 147670], and NOS3 [MIM: 163729]) were found in the “long survivor” group but not in the “stroke” group." (PMID 32898326, 2020).
tumor (18 papers, 2012 to 2025). "OGDHL is a component of the oxoglutarate dehydrogenase complex that is involved in degradation of glucose and glutamate, and has been associated with tumor development and progression." (PMID 38424222, 2024). "On the contrary, the other three downregulated genes including HMGCS2, HSD11B2, and OGDHL in higher immune score and stromal score groups indicated higher expressions of these genes were associated with more tumor purity and prognostic advantages." (PMID 31886185, 2019). "Additionally, downregulated OGDHL is associated with the advanced tumor stage, unfavorable outcome, and relapse in LIHC through reprogramming glutamine metabolism." (PMID 37229243, 2023). "In HCC, OGDHL regulates glutamine metabolic pathways and lipid synthesis, significantly affecting tumor cell growth and the response to chemotherapy." (PMID 39744494, 2025). "Conversely, oxidative metabolism genes like OGDHL were elevated alongside WWOX in good prognosis tumours." (PMID 41007296, 2025). "Promising strategies emerging include AAV-mediated OGDHL gene therapy, which has been shown in animal models to effectively suppress tumor growth and prolong survival." (PMID 41463550, 2025). "Consistent with the in vitro results, the subcutaneous tumor xenograft model with high OGDHL expression grew more slowly than controls, and the tumor mass and volume were smaller." (PMID 37626050, 2023). "The OGDHL regulates mitochondrial function, cell cycle, apoptosis, and energy metabolism in tumor cells." (PMID 37626050, 2023). "Next, the immunohistochemical results of subcutaneous xenografts also revealed that FASN expression level and tumor malignancy index KI67 decreased after OGDHL overexpression." (PMID 37626050, 2023). "We found that OGDHL acts as a tumor suppressor by inhibiting the proliferation, migration, and invasion of ccRCC cells." (PMID 37626050, 2023). "The results showed that a total of 181 samples had tumor mutation burden (TMB), of which OGDHL gene had the highest mutation frequency, followed by AOX1 and AOC1." (PMID 36185621, 2022). "In the present study, we explore the possible mechanisms closely related to the tumor microenvironment in an attempt to elucidate and comprehensively analyze the relationship between the expression of OGDHL and the prognosis of PTC." (PMID 33405394, 2021). "OGDHL expression is downregulated in HCC due to promoter hypermethylation and copy number loss, which correlates with advanced tumor stage, poor prognosis, and more frequent tumor recurrence." (PMID 41463550, 2025). "Furthermore, FTO-mediated OGDHL m 6A demethylation represses its expression in ccRCC and regulates lipid metabolism, promoting tumor progression through the FTO/OGDHL/TFAP2A/FASN axis." (PMID 40483535, 2025). "Among them, as typical representatives, ATP citrate lyase (ACLY) is highly expressed in the adipose tissue and liver, and oxoglutarate dehydrogenase-like (OGDHL) exhibits a tumor suppressor effect in HCC, which is consistent with the results of our preliminary exploration." (PMID 38282028, 2024). "It is well-known that OGDHL functions through the tricarboxylic acid cycle, and we have demonstrated that OGDHL reduces lipid accumulation in ccRCC, which is clearly another feature of OGDHL in tumor progression." (PMID 37626050, 2023). "H&E staining and in vivo imaging of small animal liver based on nude mice tail vein metastasis demonstrated that OGDHL overexpression could significantly reduce the level of tumor metastasis." (PMID 37626050, 2023). "Therefore, the interactions between OGDHL and tumor microenvironment immune cell infiltration can be a potential mechanism for correlating OGDHL expression with prognosis in PTC." (PMID 33405394, 2021). "Thus, we confirmed that OGDHL acts as a tumor suppressor in ccRCC." (PMID 37626050, 2023). "Energy metabolism favours oxidative phosphorylation and the tricarboxylic acid (TCA) cycle (OGDHL, PCK1, ACO1, FH) over glycolysis, limiting tumour growth." (PMID 41007296, 2025).
tumor (continued). "Oxoglutarate dehydrogenase-like (OGDHL) is an essential regulatory gene and a putative tumor suppressor gene." (PMID 31781311, 2019). "Our findings from the ESTIMATE algorithm also indicates that groups with different OGDHL expression levels show different tumor microenvironments, thereby further supporting the potential of OGDHL as a PTC prognostic marker closely related to the PTC tumor microenvironment." (PMID 33405394, 2021).
cancer (14 papers, 2012 to 2025). A tumor composed of atypical neoplastic, often pleomorphic cells that invade other tissues. "First, we found recurrent germline mutations in OGDHL (oxoglutarate dehydrogenase L) specific to carcinoma patients (4/11, 36%)." (PMID 37121965, 2023). "Nevertheless, an isoenzyme of 2-oxoglutarate dehydrogenase, encoded by the OGDHL gene, is down-regulated in a number of cancers, including the lung adenocarcinoma A549 cells, by promoter hypermethylation." (PMID 32466567, 2020). "Metabolic reprogramming is a hallmark of cancer, and downregulation of oxoglutarate dehydrogenase-like (OGDHL) contributes to the onset and progression of several cancers." (PMID 31781311, 2019). "KIF1A (p=0.012) and OGDHL (p=0.048) were significantly associated with BC, after adjusting for age, family history of cancer and DRC." (PMID 24927296, 2014). "OGDHL is also associated with the pathogenesis and progression of various cancers." (PMID 41463550, 2025). "OGDHL expression had excellent diagnostic value overall (AUC = 0.909) and was also able to distinguish noncancerous tissue from stage I cancer (AUC = 0.885), stage II cancer (AUC = 0.920), stage III cancer (AUC = 0.949), and stage IV cancer (AUC = 0.998)." (PMID 31781311, 2019). "This discovery significantly expands the functional repertoire of OGDHL beyond metabolism, siting it as a direct regulator of genomic integrity in cancer cells." (PMID 41463550, 2025). "Although OGDHL has been extensively studied in liver and cancer biology, its functions in the brain are often overlooked." (PMID 41463550, 2025). "Re-establishment of the OGDHL expression in the cancer types with downregulated OGDHL gene has anti-proliferative properties associated with the increased production of reactive oxygen species (ROS) by such cells." (PMID 32466567, 2020). "Many studies of OGDHL that examined its regulation of cancer have focused on methylation of its promoter region." (PMID 31781311, 2019). "We and others reported previously that OGDHL is inactivated due to promoter methylation and cancer specific promoter methylation occurs in several different cancer types." (PMID 23152800, 2012). "These properties suggest a potential growth modulating role of OGDHL in cancer; however, the molecular mechanism through which OGDHL exerts its growth modulating function has not been elucidated." (PMID 23152800, 2012). "The essential role of this complex is in the degradation of glucose and glutamate and the OGDHL gene (one component of OGDHC) is down-regulated by promoter hypermethylation in many different cancer types." (PMID 23152800, 2012). "Downregulation of OGDHL expression alters mitochondrial function, contributing to increased cellular proliferation, which can lead to the development and progression of several cancers." (PMID 40376698, 2025). "Moreover, these two SBS subtypes differed in somatic mutations in several cancer driver genes, including higher mutation frequency of ERBB2, GATA3 and FGFR4, and lower frequency of DMD, INHBA, OGDHL, PLEKHG5 and RYR2 in subtype 3 than in subtype 1 (P < 0.05)." (PMID 40858906, 2025). "Survival analysis showed that patients with lower OGDHL levels had shorter overall survival (OS), and subgroup analysis indicated this relationship also held for patients with grade G1/G2, stage I/II, T3, N0, and M0 cancers." (PMID 31781311, 2019). "We have previously shown that the promoter of OGDHL is differentially methylated in different tissue types, and cancer-specific promoter methylation was also observed in breast, cervix, lung, oesophagus, pancreas and colon cancers, while methylation was absent in ovary, kidney and bladder cancers." (PMID 23152800, 2012). "The relatively few cancer mutations included in COSMIC ten years ago limited our ability to implement stricter parameters, which may have resulted in more false positives, as demonstrated by our metabolomic screen only confirming OGDHL A400T as a COMF." (PMID 37950065, 2023).
cancer (continued). "In conjunction with our results, this suggests that the downregulation of OGDHL, which alters mitochondrial function and increases cell proliferation, might explain our observation of a correlation of low OGDHL expression with more advanced cancer." (PMID 31781311, 2019). "The contrast between expression of OGDHL and ASNS in the repeated damage model versus radiotherapy experiments suggest that the initial or innate response of cancer cells to DNA damage is down-regulation of these genes." (PMID 37196186, 2023). "UGT1A1 protein and OGDHL, a component of the OGDC enzyme complex and a key control point in the citric acid cycle often bypassed in cancer cells." (PMID 36295907, 2022). "Conversely, forced expression of OGDHL in cervical cancer downregulates AKT signaling, reduces caspase-3-mediated phosphorylation of NF-κB, enhances ROS production, which in turn induces apoptosis and inhibits cancer cell proliferation and metastasis." (PMID 41463550, 2025). "Although epigenetic study findings suggest OGDHL as a potential cancer related gene, the direct genetic evidence of growth modulating function of OGDHL is lacking." (PMID 23152800, 2012). "OGDHL, as the main rate‐limiting component of 2‐oxoglutarate dehydrogenase complex (OGDHC) for glucose and glutamic acid degradation, plays an important role in the development of a wide variety of cancers 7 and tumors by influencing cell cycle arrest, cell apoptosis, and energy metabolism." (PMID 33405394, 2021). "In addition, patients with lower OGDHL levels had shorter relapse-free survival, and subgroup analysis indicated this relationship also held for patients with grade G1/G2, stage III/IV, T1, T3, N0, and M1 cancers." (PMID 31781311, 2019).
neurodevelopmental disorder (3 papers, 2023 to 2025). A behavioral and cognitive disorder with onset during the developmental period that involves impaired or aberrant development of intellectual, motor, or social functions. "OGDHL mutations have been associated with the expanding spectrum of clinical phenotypes, ranging from severe neurodevelopmental disorders to affective symptoms and multi-systemic involvement, underscoring their multifaceted functions in the nervous system." (PMID 41463550, 2025). "Mutations in OGDHL have been linked to a range of neurodevelopmental disorders, underscoring its specialized role in maintaining neuronal function and survival." (PMID 41463550, 2025). "Oxoglutarate dehydrogenase L (OGDHL), a brain-enriched rate-limiting enzyme in the tricarboxylic acid cycle, has been tightly linked to neurodevelopmental disorders, highlighting its essential role in neural processes." (PMID 41463550, 2025). "Building on the genetic evidence that links OGDHL mutations to neurodevelopmental disorders, this section will discuss the multifaceted physiological and pathological functions of OGDHL in the nervous system." (PMID 41463550, 2025). "Biallelic variants in OGDHL, encoding part of the α-ketoglutarate dehydrogenase complex, have been associated with highly heterogeneous neurological and neurodevelopmental disorders." (PMID 38031187, 2023). "Going further, we uncovered evidence for a complex compensatory relationship among OGDH, OGDHL, and DHTKD1 isoenzymes that are associated with neurodevelopmental disorders and exhibit complex transcriptional compensation patterns with partial functional redundancy." (PMID 38031187, 2023).
neurological diseases (3 papers, 2023 to 2025). "By integrating these insights, we aim to advance the understanding of OGDHL’s functions in the nervous system and establish a foundation for elucidating the mechanisms underlying OGDHL-related neurological diseases." (PMID 41463550, 2025). "MBD5, OGDHL, AUTS2, EGR3, QPCT, and ITGA8 are linked to neurological diseases." (PMID 39588153, 2024). "Interestingly, OGDH, OGDHL, and DHTKD1 each possess a ThDP binding domain, and thiamine (vitamin B1) administration is an intriguing treatment possibility, as oral thiamine has been used to improve various neurological disorders with minimal adverse reactions." (PMID 38031187, 2023).
heart diseases (1 paper, 2022). "At present, there are few studies about OGDHL in heart diseases." (PMID 35463769, 2022).
OGDHL also shares sentences with these, for which no sentence is quoted: eosinophilic esophagitis (3 papers); Intellectual disability (2); thyroid cancer (2); Cerebral atrophy (1); colon cancer (1); colorectal adenocarcinoma (1); dilated cardiomyopathy (1); heart failure (1); movement disorder (1); neurodegenerative disease (1); Obesity (1); papillary thyroid cancer (1); parathyroid carcinoma (1); portal hypertension (1); prostate tumours (1); renal diseases (1); sarcoma (1); schistosomiasis (1).